IRF3 (interferon regulatory factor 3)
Diseases named in the same sentence as IRF3 in open-access papers (continued):
Sharing a sentence is not in itself a finding about the gene and the disease.
viral infection (continued). "In these and other studies, IRF3 was shown to be an important component of the immediate-early response to virus infection, while IRF7 is involved in the late induction phase of IFN expression during viral infection." (PMID 25798928, 2015). "Although IRF3 activation and IFN-β production are essential for the host to prevent viral infection, aberrant or excessive IFN-β production may lead to the pathogenesis of human autoimmune diseases." (PMID 25763818, 2015). "Importantly, virus infection promoted TRIM26 nuclear translocation, which was required for IRF3 degradation." (PMID 25763818, 2015). "More specifically, the overexpression of PML-VI augmented the production of IFNβ in U373-MG or HeLa cells stimulated by double RNA or virus infection, and this augmentation was attributed to the ability of PML-VI to recruit Pin1 to PML NBs, and thereby prevent the degradation of phosphorylated IRF3." (PMID 25812002, 2015). "A previous study has shown that cells lacking IRF3 are unable to produce type I IFN in viral infections and that TBK1 and IKK-I control both IRF3 and STAT1." (PMID 25942440, 2015). "Both IRF3 and IRF7 play distinct and essential roles in the IFN-α/β response to virus infection." (PMID 25798928, 2015). "Among all the IRFs, IRF3 and IRF7 are the key regulators of IFN-I expression upon viral infection." (PMID 25759845, 2015). "IRF3 and IRF7, two key transcription factors that modulate type I IFN expression, are phosphorylated, undergo homo/heterodimerization, and translocate into the nucleus upon viral infection." (PMID 26186542, 2015). "Therefore, IRF3 activation and IFN-β production must be terminated at the appropriate time points after viral infection." (PMID 25763818, 2015). "Besides IRF3, IRF7 is another main regulator of TLR-mediated type I IFN response to virus infection." (PMID 24722640, 2014). "IFN-regulatory factor 3 (IRF3), a ubiquitously expressed transcription factor, is responsible for the primary induction of IFN and is a crucial player in the establishment of innate immunity in response to viral infection." (PMID 24586174, 2014). "Upon viral infection, MITA translocates to intracellular membrane-containing compartments to form punctate aggregates and acts as a scaffold protein to facilitate the phosphorylation of IRF3 and STAT6 by the kinases TBK1 and IKKε." (PMID 25254379, 2014). "In addition, we show here that PML enhanced both IRF3 activation and IFN-β synthesis upon viral infection." (PMID 24586174, 2014). "Unlike wild-type MAVS, which activated IRF3 and formed SDS-resistant aggregates following viral infection, MAVS containing point mutations in the CARD domain failed to activate IRF3 or form aggregates." (PMID 23951545, 2013). "Alternatively, in MAVS−/− and IRF3−/−IRF7−/− cells, minute, steady state amounts of IFNs could still be produced and be sufficient to induce ISGs in a context of viral infection." (PMID 24278020, 2013). "In the early phase of viral infection, IFN-regulatory factor 3 (IRF3) and IRF7 are phosphorylated at specific serine residues, resulting in the homodimerization or heterodimerization of the IRF3 and IRF7." (PMID 23118935, 2012). "However, TRAF3 was demonstrated to link the mitochondrial membrane-bound protein MAVS to the activation of TBK1, which is required for IRF3/7 phosphorylation and type I IFN induction in response to viral infection." (PMID 22792062, 2012). "Upon virus infection, PI3K is activated and mediates activation of the transcription factor IRF-3." (PMID 19592477, 2011). "Thus, IRF7 is particularly important for the continued expression of IFN-β during viral infection, and also contributes to induction of IFN-β by co-operation with IRF3." (PMID 21931555, 2011). "We showed that, when immunoprecipitated, IRF3 efficiently co-precipitates HA-ORF47 even in absence of viral infection (lanes 6 & 7)." (PMID 21347389, 2011).
viral infection (continued). "Since the interferon regulatory factor-3 (IRF-3) contributes to a first line of defence against virus infection, we investigated whether the BTV infection of mammalian cells results in the activation of IRF-3 and related IRF-7." (PMID 21134281, 2010). "The binding of IRF-3 and the large number of potential binding elements near TSS II suggest that this promoter is regulated by the interferon directed innate immune response to viral infection." (PMID 21062477, 2010). "In contrast, lack of IRF3 or that of IRF7 resulted in significant reduction or abrogation of the viral infection-induced type I IFN production, respectively." (PMID 19479062, 2009). "The findings that IKKγΔ expression reduces IRF3 signaling and type I IFN response in response to ssRNA virus infection may yield new insight for tissue-selective differences in anti-viral responses and tissue tropism in RNA virus infections." (PMID 19956647, 2009). "Triad3A was induced following dsRNA exposure or virus infection and decreased TRAF3 levels in a dose-dependent manner; moreover, Triad3A expression blocked IRF-3 activation by Ser-396 phosphorylation and inhibited the expression of type 1 interferon and antiviral genes." (PMID 19893624, 2009). "Single stranded RNA (ssRNA) virus infection activates the retinoic acid inducible gene I (RIG-I)- mitochondrial antiviral signaling (MAVS) complex, a complex that coordinates the host innate immune response via the NF-κB and IRF3 pathways." (PMID 19956647, 2009). "Moreover, enveloped virus particles by themselves can activate IRF-3 in a TLR- and RIG-I-independent manner, implicating that mammalian hosts can respond to several independent hallmarks of virus infection." (PMID 18446221, 2008). "Although IRF3 has been shown to mediate TNF induction under various circumstances, such as lipopolysaccharide stimulation or certain viral infections, the collaboration between IRF3 and IRF7 resulting in sustained TNF induction has not been recognized before." (PMID 18617992, 2008). "Moreover, glucose restriction may reduce lactate production and relax lactate-mediated inhibition of MAVS, IRF3, and NF-κB signaling, enhancing the IFN-I response and impairing viral infection." (PMID 40391966, 2025). "The activation of this pathway stimulates the expression of the IFN-regulatory factor 3 (IRF3) transcription factor, which results in the induction of IFN gene transcription and subsequent downstream proinflammatory chemokine production, which provides protection against viral infections." (PMID 40431442, 2025). "Furthermore, the expression of IRF3 was higher in Rnf149−/− macrophages compared to WT macrophages and the level of IRF3 did not change with the increase of virus infection time." (PMID 40245000, 2025). "In mice, Irf3 prolyl hydroxylation at P10 appeared to be reduced after VSV infection for 24 h, suggesting that a negative feedback mechanism might exist by altering Irf3 hydroxylation in response to viral infection." (PMID 38670937, 2024). "Notably, the interaction between IRF3 and EGLN1 was stable during viral infection." (PMID 38670937, 2024). "However, KAT8 can also influence macrophage function in response to viral infections by directly acetylating a non-histone protein, interferon regulatory factor 3 (IRF3)." (PMID 38790268, 2024). "Additionally, increased level of signaling molecules IRF-3 and TBK1 observed in the Berb-treated group indicate activation of the IRF-3-TBK-1 pathway, enhancing the expression of IFN-β, IFITM, and OAS1g, which are crucial in combating viral infections." (PMID 39640591, 2024). "For example, in epithelial and fibroblast cells low levels of viral infection can be prevented by IRF3-induced ISGs even before virus replication and without IFN or proinflammatory cytokine secretion, thus bypassing the inflammatory effects associated with IFN signaling." (PMID 39302126, 2024).
viral infection (continued). "In contrast to infected cells, IRF3 and NF-κB were homogenously distributed in the cytoplasm of adjacent non-infected cells (asterisks), showing that the transcription factors were not activated in the absence of viral infection." (PMID 36851768, 2023). "YAP interacts with interferon regulatory factor 3 (IRF3), the final downstream effector of IKK signaling and a key transcription factor in innate immunity, preventing dimerization and nuclear translocation, which reduces IFN-β production in response to viral infection." (PMID 37397250, 2023). "Our results showed that IRF3/5/7 are expressed in cytoplasm, generally in an inactive state like their mammalian counterparts, and after stimulation by poly(I:C) and TBK1 transfection or virus infection, they rapidly undergo the cytoplasmic to nuclear translocation." (PMID 35464458, 2022). "However, our results show that viral infection or genetic knockout of lincRNA‐EPS facilitates PKR‐STAT1 signaling axis induced antiviral genes such as Mx1, Oas2, Ifit2, and Irf7, while inhibits phosphorylation of TBK1 and IRF3, as well as the IFN‐β induction." (PMID 35312140, 2022). "No obvious effects on either the phosphorylation or dimerisation of IRF3 were detected following knockdown of the Bag6 protein, suggesting that the BAG6 complex is not an essential component for the cellular mobilisation of a MAVS-dependent response to viral infection." (PMID 35543156, 2022). "Interestingly, while IRF3 nuclei translocation occurred exclusively in infected cells, we observed that IRF1 accumulation in the nuclei occurred mostly in bystander cells, confirmed by ZIKV dsRNA staining, which shows the early stage of virus infection." (PMID 36311766, 2022). "Interestingly, a role for IRF3-mediated apoptosis has also been described in the study of liver diseases, suggesting the physiological role of RIPA may extend beyond virus infection." (PMID 33805458, 2021). "Furthermore, viral infection triggers various molecular pathways downstream of these PRRs, which converge to recruit Tank-binding Kinase 1 (TBK1) and homologue IκB kinase epsilon (IKKε), to activate interferon regulatory factor 3 (IRF3)." (PMID 33419081, 2021). "Therefore, we demonstrated the interplay among the nuclear proteins including chromotin remodeler ARID1A, transcriptional factor IRF3, and histone modification protein NSD2 at the Ifn-I promoter regions which jointly regulate the production of IFN-I in innate immune cells upon virus infection." (PMID 34315861, 2021). "In addition, IRF-3 was degraded after 9 h post-viral infection, while the protein level of IRF3a did not change significantly." (PMID 34868032, 2021). "In addition, N protein affected the phosphorylation and nuclear translocation of transcription factor IRF3, which is essential for IFN-β production upon virus infection, further indicating that N protein plays an important role in antagonizing the IFN-β response." (PMID 33396605, 2020). "Moreover, the other antiviral response markers selected for this study in red tilapia, including irf-3, Mx, and VIPERIN (or rsad-2), were previously found to be strongly induced during several viral infections in other teleosts and involved in the IFN response in tilapia." (PMID 33172079, 2020). "Combined with our previous finding that NF-κB P65 could directly mediate the transcription of CXCL16 in keratinocytes through directly binding to the promotor of CXCL1645, we draw a conclusion that CXCL16 is mainly elaborated by IRF3 and NF-κB in the downstream of MAVS under virus infection." (PMID 32532953, 2020). "However, the antiviral activity of type I IFNs against PRRSV infection remains unclear, here we demonstrated that the deactivated IRF3 by PP2A inhibited the type I IFN signaling pathway and facilitated the viral replication step during virus infection." (PMID 31618847, 2019).
viral infection (continued). "(2017) showed that lncRNA aconitate decarboxylase 1 (ACOD1) might be induced by viral infection through a pathway that is independent of interferon regulatory factor 3 (IRF3)/type I IFN (IFN‐I) signalling, but dependent on the NF‐κB‐dependent pathway." (PMID 30499165, 2019). "sIL6 has been shown to be induced by viral infection, and sIL-6R mediated antiviral activation via the p28 pathway and IFN-α could promote nuclear translocation of IFN regulatory factor 3 (IRF3) and NF-κB, thereby inducing activation of downstream IFN effector molecules such as 2′5′OAS, PKR, and Mx." (PMID 29118754, 2017). "Interestingly, even in the absence of viral infection, IRF-3 levels are higher in Muc18 KO cells, suggesting an inhibitory effect of MUC18 on antiviral gene expression at the upstream signaling level." (PMID 27701461, 2016). "In summary, it has been demonstrated that upon virus infection, the SNRNP200 RNA helicase in combination with TBK1 via its Sec63-1 domain recognizes viral RNA, relocalizes into TBK1-containing cytoplasmic structures, and positively regulates IRF3 phosphorylation to promote the antiviral response." (PMID 27454487, 2016). "This may explain why WT IRF3 was degraded without virus infection and the level of total IRF3 was decreased in TRIM26-Tg mice." (PMID 25763818, 2015). "However, in our study, we did not observe any changes of IRF3 induction upon virus infection, implying a lack of IFN responses to SINV infection." (PMID 25343994, 2014). "In addition, we confirmed that JNK2 did not directly modulate the IRF3 or NF-κB signaling pathways during virus infection by using the corresponding reporter systems in both JNK1/JNK2 siRNA knock down cells and JNK1/JNK2 overexpressing cells." (PMID 24651600, 2014). "Upon viral infection, the cytosolic receptors RIG-I and MDA5 can detect viral genome RNA or replication byproduct dsRNA to induce multiple signaling pathways, and eventually activate transcription factors IRF3 and NF-κB, which subsequently translocate into nucleus and initiate IFN transcription." (PMID 22412872, 2012). "In addition, rapid degradation of IRF3 was recently shown to play a critical role in the negative regulation of IFN-B gene expression during acute viral infection." (PMID 22685561, 2012). "In addition to controlling constitutive ifnβ expression, NF-κB is also the earliest-arriving virus-activated enhanceosome component, appearing on the ifnβ enhancer within 2 hours of virus infection (and approximately 2 and 4 hours ahead of ATF-2 and IRF-3, respectively)." (PMID 22022260, 2011). "The decrease in expression of pGL3-PURA in the presence of overexpressed IRF-3, IRF-5, and IRF-7 and the specific binding of IRF-3 to sequence near TSS II led us to investigate whether or not viral infection could affect PURA transcription." (PMID 21062477, 2010). "However, CHX treatment resulted in enhanced IRF3 activation in the absence of viral infection upon DNA sensing stimulation for reasons that remain unclear (not shown)." (PMID 39431915, 2024). "USP22 controls nuclear accumulation of IRF3 and type I IFN signaling through KPNA2 deubiquitination only upon infection with SeV and HSV-1 and loss of USP22 expression decreased type I IFN responses upon virus infection, while USP22 deletion in uninfected cells did not trigger basal IFN signaling." (PMID 35933402, 2022). "Then, the higher expression of IRF3, IFN-β and IFN-λ1 found in porcine alveolar macrophages treated with HK36, HK39 or HK40 allow us to speculate that these postimmunobiotics could have beneficial effects in the protection of the respiratory tract against viral infections in the porcine host." (PMID 36230948, 2022). "Moreover, recent studies suggest that recruitment of TBK1 to STING may perform a more significant role in antagonist virus infection and restrict oncogenesis, which expands the horizon of cGAS-STING axis function besides IRF3 and nuclear factor-κB (NF-κB) signaling." (PMID 34966372, 2021).
viral infection (continued). "Indeed, it can be inferred that AHR may influence viral infection through impacting IRF-3 independent of IFN." (PMID 34668726, 2021). "This dual binding may conformationally rearrange the IRF3 protein that might hinder the phosphorylation step at the Ser-patches and is the likely reason why it is not necessary for E6 to either destroy or ubiquinate IRF3 to facilitate viral infection, as it simply precludes its activation." (PMID 26289783, 2015). "However, N2 reduced the expression of chemokine CXCL10, which is regulated by an IRF3-responsive promoter, from cells infected with Newcastle disease virus (NDV), providing further evidence of its ability to inhibit the IRF3-dependent innate immune response to virus infection." (PMID 23761407, 2013). "Thus, the sequential involvement of IRF3 and IRF7 in the early and later phase of TNF production allows us to postulate that, if the early phase production of TNF and type I IFN is sufficient to block viral infection, then the later phase production of both cytokines will be coordinately curtailed." (PMID 18617992, 2008). "As a control, C156-P1 treatment alone, without virus infection, did not change the levels of phosphorylated TBK1 and IRF3." (PMID 41004242, 2025). "In chickens, where IRF3 is absent, IRF7 is utilized to reconstitute the corresponding IFN signalling pathway in response to viral infection." (PMID 40108733, 2025). "The results revealed that overexpression of DYRK4 stabilized the exogenous or endogenous IRF3 protein, and under conditions of viral infection, overexpression of DYRK4 extended the half-life of the exogenous IRF3 protein but did not affect IRF3 transcription." (PMID 39702801, 2025). "In conclusion, our study revealed an underlying mechanism of how NOG1 negatively regulates IFN-β by targeting IRF3, which would contribute to understanding the negative regulation of host innate immune responses and the function of NOG1 during virus infection." (PMID 37410776, 2023). "Honda and Taniguchi reported that the homodimer of IRF7 or the heterodimer of IRF7/IRF3, rather than the homodimer of IRF3, is more important for the production of IFN-I under viral infection." (PMID 37638030, 2023). "To explore the potential role of USP12 in antiviral immunity, we first detected the expression of USP12 after virus infection and found that USP12 expression was induced by HSV-1 infection, which was mainly regulated by NF-κB p65 and IRF3, but not by STAT1." (PMID 37410794, 2023). "The induction of MVP expression by viral infection upregulates type-I interferon production by enhancing the expression of IRF7 (interferon regulatory factor 7), but not IRF3 (interferon regulatory factor 3)." (PMID 35681764, 2022). "Stimulation of RLRs with dsRNA or viral infection induces MAVS-dependent ubiquitination of IRF3 and subsequent activation of pro-apoptotic factors independent of IRF3’s transcriptional activity." (PMID 35436994, 2022). "We did not detect phosphorylation of IRF3 and STAT1 in A549 cells of RUNX1 knockdown or overexpression without virus infection." (PMID 35248104, 2022). "Given that IRF7 plays a predominant role in the late phase of viral infection, it is conceivable that NEURL3 preferentially regulates the activity of IRF7 rather than IRF3." (PMID 35792897, 2022). "Actually, for both viruses, KO of individual IRFs did not noticeably affect IFN production, surprisingly not even the KO of IRF3, which was thought to be a major factor for the induction of type I and III IFN upon virus infection." (PMID 34685580, 2021). "Consistently, P5 fraction isolated from sh-Ube2N-treated MEFs showed no activity in stimulating IRF3 dimerization, suggesting that MAVS was not activated on virus infection." (PMID 28469175, 2017). "IRF7 is largely responsible for IFN production in response to viral infection, as evidenced by the abrogation of IFN production in Irf7 −/− mice, but not in Irf3 −/− mice." (PMID 23555825, 2013).